SFPQ (splicing factor proline and glutamine rich)
Diseases named in the same sentence as SFPQ in open-access papers (continued):
Sharing a sentence is not in itself a finding about the gene and the disease.
lung carcinoma (5 papers, 2020 to 2025). "Considering this, SFPQ expression and its subcellular location is a special feature and can serve as a diagnostic and treatment-monitoring marker in lung cancer." (PMID 37569873, 2023). "These demonstrate that loss of SFPQ expression significantly decreased the invasive phenotype of NSC lung cancer-MSCs." (PMID 35707369, 2022). "While SFPQ normally resides in the nucleus, it can be found in other subcellular locations in lung cancer cells." (PMID 40770831, 2025). "Subcellular fractions of controls, IPF, inflammatory lung disease cells, and lung cancer cells were isolated and used to analyze SFPQ isoforms." (PMID 37569873, 2023). "Following the inhibition of DNA methylation in lung cancer cells, the DNA methylation level in SFPQ promoters decreased, which led to an increase in SFPQ expression." (PMID 37569873, 2023). "How SFPQ affects cancer cell stemness and its upstream regulators are unclear, and mechanism works among SFPQ, CD44v6, and other proteins in lung cancer MSCs need be further investigated." (PMID 35707369, 2022). "In vivo study, knockdown of SFPQ in NSC lung cancer-MSCs reduces their ability to metastasize distantly, which suggests that SFPQ is a potential therapeutic target for cancer metastasis, although clear mechanisms need to be described." (PMID 35707369, 2022). "Our results suggest that SFPQ is critical in the stemness, proliferation, chemoresistance, and cell invasion of lung cancer MSCs." (PMID 35707369, 2022). "Together, this data indicates that SFPQ plays a key role in promoting the metastasis of NSC lung cancer-MSCs in vivo." (PMID 35707369, 2022). "YY1, RTN4, RICTOR, SFPQ, LARP6, and HELLS have been associated with cancers previously and, in this study, exhibited differential level changes between control, Idiopathic Pulmonary Fibrosis (IPF) and lung cancer cells." (PMID 37569873, 2023). "We then explored a possible mechanism for the SFPQ isoform changes seen in lung cancer." (PMID 37569873, 2023). "Since the short SFPQ isoform is only present in the cytoplasm of lung cancer cells, this SFPQ isoform distribution could be a potential marker for clinical tests for lung cancer." (PMID 37569873, 2023). "Our findings suggest that SFPQ and its isoforms may serve as markers for lung cancer and other solid cancers." (PMID 37569873, 2023). "We have discovered DNA methylation differences in the SFPQ promoter region which may be responsible for the SFPQ isoform expression differences between lung cancer and IPF and normal cells." (PMID 37569873, 2023). "Moreover, a regulator named SFPQ was shown to be overexpressed and to promote lung cancer malignancy via CD44 v6 expression." (PMID 38069324, 2023). "We found the CD44v6 was co-localized with SFPQ in the nucleus of NSC lung cancer-MSCs." (PMID 35707369, 2022). "These suggest that SFPQ regulates stemness and self-renewal in lung cancer-MSCs." (PMID 35707369, 2022). "CD44 is a protein involved in cancer initiation and development and highly affected by RNA splicing, thus we hypothesized that CD44 splicing were regulated by abnormal expression of SFPQ in lung cancer." (PMID 35707369, 2022). "Our proteomics analysis of MSC nuclear fraction, bioinformatics, and functional analysis with lung cancer MSCs found that SFPQ (Splicing Factor Proline and Glutamine Rich) is the top upstream regulator of lung cancer MSC cell activity when compared with control MPCs." (PMID 35707369, 2022). "Taken together, SFPQ is present on the cell surface and affects cell function via interaction with S100A4, PPIA, etc. in lung cancer and other solid cancer cells." (PMID 40770831, 2025). "In vivo study, lung cancer cells A549, H648 and H661 were intravenous; (IV) injected into NSG mice, and anti‐SFPQ 1A6 or control IgG was applied to the mice six times in intervals of 3 days." (PMID 40770831, 2025). "SFPQ, RTN4, HELLS, RICTOR, and LARP6 have high expression in lung cancer and other cancer cells and tissues." (PMID 37569873, 2023).
lung carcinoma (continued). "IF staining with the primary cell lines led to a similar result; however, the results displayed a positive anti-SFPQ N-terminal stain with lung cancer cells but not control and IPF cells." (PMID 37569873, 2023).
neoplasm with perivascular epithelioid cell differentiation (5 papers, 2022 to 2025). A soft tissue neoplasm composed of perivascular epithelioid cells. "The SFPQ/TFE3 gene fusion is also present in perivascular epithelioid cell tumours (PEComas) and melanotic Xp11 translocation renal cancers." (PMID 40276932, 2025). "Recent studies have revealed the presence of TFE3 gene rearrangements in 23% of PEComas, which involve the formation of gene fusions such as SFPQ/PSF::TFE3 and DVL2::TFE3." (PMID 38291475, 2024). "After their discovery in papillary renal cell carcinoma (PRCC) as PRCC-TFE3 gene fusion, further partnerships have been reported, including NONO, SFPQ, and DVL2 genes in papillary renal cell carcinomas and PEComas." (PMID 35225876, 2022).
hepatocellular carcinoma (4 papers, 2020 to 2024). A malignant tumor that arises from hepatocytes. "This study systematically analyzed the complex relationship between paraspeckle genes, angiogenesis, and tumor immunity, determining that elevated expression of SFPQ, DDX39B, and UBAP2 is closely associated with poor prognosis in hepatocellular carcinoma (HCC) patients." (PMID 39133261, 2024).
ovarian carcinoma (4 papers, 2011 to 2022). A malignant neoplasm originating from the surface ovarian epithelium. "Since SRSF2 is often overexpressed in ovarian cancer and mutated in PT-treated ovarian cancer, we have focused on the interaction between SFPQ, p54nrb, and SRSF2." (PMID 32332923, 2020). "In epithelial ovarian cancer cells, the SFPQ/SRSF2 pathway has been shown to play a key role in regulating chemotherapy-induced apoptosis." (PMID 35707369, 2022). "Splicing factor SFPQ regulated alternative splicing of caspase-9 mRNA and was involved in ovarian cancer sensitivity to platinum." (PMID 34966670, 2021). "The remaining 10 genes havenot been investigated in ovarian cancer and include SFPQ which hasbeen suggested to function as an androgen receptor co-regulator." (PMID 21423607, 2011). "Our data demonstrate that the expression levels of SRSF2, SFPQ or p54nrb impact on the sensitivity of ovarian cancer cells to PT-induced death and support the possibility that targeting alternative splicing, could also represent a promising therapeutic option to overcome PT resistance." (PMID 32332923, 2020).
liver cancer (3 papers, 2021 to 2024). An epithelial or non-epithelial malignant neoplasm that arises from the liver. "LncRNA NEAT1_2, on the other hand, does not affect the transcription and translation levels of SFPQ, but at least partially mediates cisplatin resistance in liver cancer cells through SFPQ." (PMID 39532842, 2024). "Additionally, DHX9 interacts with NONO and SFPQ to form a DHX9-NONO-SFPQ complex, a key regulator in liver cancer." (PMID 34512155, 2021).
tauopathies (3 papers, 2013 to 2022). "However, future pathological studies examining the FUS/SFPQ nuclear interaction in both FTLD/ALS and tauopathies are necessary." (PMID 29774215, 2018).
dementia (2 papers, 2012 to 2020). Loss of intellectual abilities interfering with an individual's social and occupational functions. "Strikingly, in AD and PiD, both dementias with a tau pathology, affected brain areas showed a virtually complete nuclear depletion of SFPQ in both neurons and astrocytes, along with cytoplasmic accumulation." (PMID 22558197, 2012). "Within the sensitivity of the western blot, the band for SFPQ was not detectable, which coincided well with the reduced levels of SFPQ in the post-mortem brains, in rapidly-progressive forms of dementia (rpAD and sCJD)." (PMID 32577828, 2020).
gastric cancer (2 papers, 2024 to 2025). A primary or metastatic malignant neoplasm involving the stomach. "However, despite their roles in maintenance of highly restricted forms of latency present in Burkitt lymphoma andnasopharyngeal and gastric carcinomas, our data suggest that neither SFPQ nor histone H1 play obligatory roles at the earliest stages of EBV latency establishment." (PMID 38755141, 2024).
melanoma (2 papers, 2021 to 2025). A malignant, usually aggressive tumor composed of atypical, neoplastic melanocytes. "We report that knockdown of SFPQ expression in melanoma cells decelerates several cancer-associated cell phenotypes, including cell growth, migration, epithelial to mesenchymal transition, apoptosis, and glycolysis." (PMID 34218270, 2021). "Together, these data demonstrate that increased expression of SFPQ in primary melanoma is associated with decreased melanoma patient survival and that SFPQ expression may have some utility as prognostic biomarker in primary melanoma." (PMID 34218270, 2021). "The multifunctional protein, splicing factor, proline- and glutamine-rich (SFPQ) has been implicated in numerous cancers often due to interaction with coding and non-coding RNAs, however, its role in melanoma remains unclear." (PMID 34218270, 2021). "Together, these data demonstrate that SFPQ contributes to the efficient expression of several melanoma-associated oncogenic transcripts in a predominantly RNA stability-independent manner, and by doing so contributes to the maintenance of a ‘cancer transcriptomic state’ in melanoma cells, in vitro." (PMID 34218270, 2021). "For example, SFPQ interacts with RNA to promote the expression of oncogenic transcripts in melanoma." (PMID 39856764, 2025). "Together, these data suggest that SFPQ is an important driver of melanoma, likely due to SFPQ–RNA interactions promoting the expression of numerous oncogenic transcripts." (PMID 34218270, 2021). "Together, these data demonstrate that knockdown of SFPQ in melanoma cells results in a wide-ranging attenuation of the cancer cell phenotype." (PMID 34218270, 2021). "To investigate the role of SFPQ in melanoma, we analysed SFPQ protein expression in untransformed primary human melanocytes (PM) alongside a range of melanoma cell lines." (PMID 34218270, 2021). "Given data demonstrating a role for SFPQ in melanoma cell phenotype, we were keen to characterise the SFPQ-RNA interactome in PM and establish if this was reprogrammed in melanoma cells." (PMID 34218270, 2021). "Given the importance of dysregulated respiration in melanoma biology we also investigated if SFPQ knockdown affected cellular respiration via real-time analysis of oxygen consumption rate (OCR)." (PMID 34218270, 2021). "Here we investigated the role of SFPQ in melanoma cells and showed that expression of SFPQ contributes to melanoma cell growth, migration, apoptosis, glycolysis, and epithelial to mesenchymal transition (EMT)." (PMID 34218270, 2021). "In summary, we have shown that SFPQ positively contributes to the cancer phenotype in melanoma, likely via reprograming of the SFPQ-RNA interactome in melanoma to favour the expression of oncogenic transcripts." (PMID 34218270, 2021). "The role of SFPQ in melanoma is less clear, with a single article suggesting SFPQ attenuates RAB23 expression via binding of the lncRNA, LLME23." (PMID 34218270, 2021). "Given the widely documented relationship between SFPQ and lncRNAs in several cancers, including melanoma, SFPQ interactors were also ranked according to their PM- and A2058-specificity." (PMID 34218270, 2021). "To investigate if SFPQ expression groups in primary melanoma tumours were prognostic for survival, we utilised our previously published transcriptomic data from the primary melanomas of 703 patients, which comprises part of the Leeds Melanoma Cohort (LMC)." (PMID 34218270, 2021). "Our observation that melanoma-specific SFPQ-enriched genes were significantly decreased following SFPQ knockdown and increased in cells overexpressing FLAG-SFPQ supports a role for SFPQ in efficient expression of bound-transcripts, rather than endogenous post-transcriptional processing events." (PMID 34218270, 2021). "Together, these data suggest that SFPQ may actively drive melanoma development." (PMID 34218270, 2021).
melanoma (continued). "Finally, analysis of our melanoma patient data revealed that high levels of SFPQ expression in tumours negatively correlate with patient survival, suggesting that SFPQ may have utility as a prognostic biomarker." (PMID 34218270, 2021). "Furthermore, knockdown of SFPQ led to a significant decrease in many of these enriched transcripts, including the lncRNA, LINC00511, which we showed contributes to the melanoma cell phenotype." (PMID 34218270, 2021).
nasopharyngeal carcinoma (2 papers, 2020 to 2024). A carcinoma arising from the nasopharyngeal epithelium. "Here, we identified the nuclear protein SFPQ as critical for highly restricted forms of B and epithelial cell latency, including in the contexts of Burkitt lymphoma and gastric and nasopharyngeal carcinomas." (PMID 38755141, 2024).
osteoarthritis (2 papers, 2023 to 2024). A noninflammatory degenerative joint disease occurring chiefly in older persons, characterized by degeneration of the articular cartilage, hypertrophy of bone at the margins and changes in the synovial membrane. "Since we confirmed the low expression of SFPQ in osteoarthritis patients, the literature has suggested that SFPQ protein is necessary for the formation of parinuclear plaques." (PMID 36915153, 2023). "The osteoarthritis therapeutic effect of p-15 requires SFPQ/Akt/RUNX2 signaling." (PMID 36915153, 2023). "This study found abnormal expression of SFPQ in patients with AS, and previous studies have found that regulating the SFPQ-AKT-RUNx2 pathway can reduce chondrocyte injury and the progression of osteoarthritis." (PMID 38770048, 2024). "P-15 can mitigate chondrocyte damage and osteoarthritis progression by inhibiting cell death and modulating SFPQ-Akt-RUNX2 pathway, offering an opportunity to develop new strategies for the treatment of osteoarthritis." (PMID 36915153, 2023). "The activity of SFPQ and RUNX2 in the bone tissue of patients with osteoarthritis was analyzed using quantitative real-time polymerase chain reaction (qRT-PCR)." (PMID 36915153, 2023). "The results showed that the expression of SFPQ was significantly decreased and the expression of RUNX2 was significantly increased in osteoarthritis cartilage tissue." (PMID 36915153, 2023). "To clarify the relationship between P-15 regulation of chondrocyte proliferation and SFPQ-Akt-RUNX2 pathway, we chemically detected the expression of SFPQ and RUNX2 in the bone joint samples from clinical osteoarthritis and non-osteoarthritis patients." (PMID 36915153, 2023). "There is no doubt that SFPQ is a key regulator of the RUNX2 gene, and targeting the SFPQ site may be a potential strategy for the treatment of osteoarthritis, and even various human cancers that presence of high levels of RUNX2." (PMID 36915153, 2023).
Achalasia (1 paper, 2023). A disorder of esophageal motility characterized by the inability of the lower esophageal sphincter to relax during swallowing and by inadequate or lacking peristalsis in the lower half of the body of the esophagus. "Analysis of DEGs showed the common upregulations of SFPQ, KLF2, and CYBA and common downregulations of JUNB, FAM118A, and C21orf33 in peripheral blood lymphocytes of achalasia." (PMID 37542039, 2023).
Arthritis (1 paper, 2023). Inflammation of a joint. "The changes in SFPQ and RUNX2 expression in patients with OA indicate the potential importance of SFPQ and RUNX2 in the progression of arthritis." (PMID 36915153, 2023).
atherosclerosis (1 paper, 2020). A disease characterized by the build-up of fatty material and calcium deposition in the arterial wall resulting in partial or complete occlusion of the arterial lumen.
B-cell acute lymphoblastic leukemia (1 paper, 2024). A neoplasm of lymphoblasts committed to the B-cell lineage, typically composed of small to medium-sized blast cells. "SFPQ, an ABL1-binding protein, drives the development of B-cell acute lymphoblastic leukemia." (PMID 40453362, 2024).
COVID-19 (1 paper, 2025). A disease caused by infection with severe acute respiratory syndrome coronavirus 2. "Motif enrichment analysis of sequences proximal to chimeric splice junctions found in COVID-19 patients versus those found in GTEx whole blood revealed two RNA binding proteins previously implicated with coronavirus infection, PTBP1 and SFPQ." (PMID 40110491, 2025).
enterovirus infection (1 paper, 2018). "If a cellular protease was targeting SFPQ during enterovirus infection, the cleavage pattern for SFPQ would be expected to be identical." (PMID 30142213, 2018).
esophageal adenocarcinoma (1 paper, 2021). A malignant tumor with glandular differentiation arising predominantly from Barrett mucosa in the lower third of the esophagus. "The expression levels of CSE1L, RPS15A, SFPQ, and CAPZB in ESCC were significcantly higher than those in normal tissue and esophageal adenocarcinoma (EAC)." (PMID 33842377, 2021).
hypospadias (1 paper, 2020). Hypospadias is the displacement of the urethral meatus on the ventrum of the penis. "FGFR2, whose mutations were associated with hypospadias, might be coregulated by SFPQ and HNRNPA1." (PMID 32316190, 2020).
influenza (1 paper, 2025). An acute viral infection of the respiratory tract, occurring in isolated cases, in epidemics, or in pandemics; it is caused by serologically different strains of viruses (influenzaviruses) designated A, B, and C, has a 3-day incubation period, and usually lasts for 3 to 10 days. "SFPQ, previously found to be involved in influenza transcription, was more recently found to interact with the SARS-CoV-2 genome and contribute to viral RNA amplification." (PMID 40110491, 2025).
intellectual disability syndrome (1 paper, 2023). "NonO, which forms heterodimers with SFPQ, is associated with an intellectual disability syndrome, including macrocephaly and a thickened corpus callosum." (PMID 36674445, 2023).
ischemic stroke (1 paper, 2018). A stroke disorder caused by obstruction of blood flow to the brain, due to thrombotic (local blood clot formation) or embolic (due to a blood clot or other material traveling from another site) event. "Notably, 15 aggregating proteins after ischemic stroke were RNABPs linked to ALS and FTD, among them TDP43 and hnRNPA18,17, as well as PSF/SFPQ and p54/NONO, two paraspeckle proteins with emerging roles in ALS18,19." (PMID 29426953, 2018).
kidney cancer (1 paper, 2025). Primary or metastatic malignant neoplasm involving the kidney. "Notably, SFPQ, a close family member of NONO and PSPC1, has been identified as essential for the survival of both TFE3 fusion and non-fusion kidney cancer cells." (PMID 41027885, 2025).